TRIM28 (tripartite motif containing 28)
Diseases named in the same sentence as TRIM28 in open-access papers (continued):
Sharing a sentence is not in itself a finding about the gene and the disease.
cancer (continued). "TRIM28 regulation of XAF1 was verified in multiple cancer cell lines." (PMID 39532800, 2024). "However, in RCC and early LC, TRIM28 plays an anti-cancer role, indicate that TRIM28 plays a dual role in the occurrence and development of tumors and is related to the background of the tumor, which requires further research." (PMID 39100077, 2024). "The development of targeted therapeutic approaches may benefit from a better understanding of the precise mechanisms by which TRIM28 influences various cancer types." (PMID 39534556, 2024). "TRIM28’s binding with MAGE proteins expands the role of TRIM28 in cancer signaling crosstalk." (PMID 39451518, 2024). "It explored the vital role of TRIM28 in epigenetics, immune processes, and cancer therapy." (PMID 39534556, 2024). "Unraveling the precise mechanisms by which TRIM28 influences different cancer types could offer valuable insights for the design of targeted therapeutic approaches." (PMID 39534556, 2024). "Furthermore, immunohistochemistry (IHC) staining confirmed higher expression of TRIM28 and pS824-TRIM28 in highly invasive cancer subtypes (HER2, Basal-like)." (PMID 39100077, 2024). "This review demonstrated the role of TRIM28 in health and diseases specially cancers." (PMID 39534556, 2024). "Additionally, TRIM28’s functions in maintaining stem cell attributes and silencing TEs further illustrate its multifaceted contribution to cancer progression." (PMID 39534556, 2024). "TRIM28/TIF1B gene expression exhibits strong positive associations with sarcoma tumors and serves as a prognostic predictor of immunotherapy resistance, regulating stemness, proliferation, and migration of cancer cells." (PMID 39009887, 2024). "Understanding the complex regulatory functions of TRIM28 in cancer could provide valuable insights into novel strategies for cancer treatment." (PMID 39534556, 2024). "TRIM28 may affect the epigenetic landscape of cancer cells by controlling the relationships between various protein families, so fostering an environment that is favorable to malignancy and resistance to treatment." (PMID 39534556, 2024). "Despite their structural similarity and frequent dysregulation in multiple human cancers, only TRIM28 shows the property to interact with XAF1, suggesting that XAF1 may recognize unique amino acid sequences in the RING domain of TRIM28." (PMID 39532800, 2024). "Gaining insight into the entire range of TRIM28’s roles in cancer biology may help create more specialized and successful cancer treatments." (PMID 39534556, 2024). "For example, both FBXW7 and TRIM28 were highly expressed in all cancer types." (PMID 37845222, 2023). "TRIM28 may act as an oncogene to promote the proliferation and survival of cancer cells and promote EMT to enhance the migration and invasion ability of cancer cells." (PMID 36756159, 2023). "TRIM28 may also be an attractive pharmacological target for enhancing the effects of radiotherapy and immunotherapy in cancer therapy." (PMID 36756159, 2023). "The immunological effects of TRIM28 on cancers are crucial to determine which cancers may benefit from anti-TRIM28 immunotherapy on a pan-cancer basis." (PMID 37781084, 2023). "Besides the diverse biological contexts in different cancers, diversity of TRIM28's biochemical activities also contributed to the complexity." (PMID 36935008, 2023). "TRIM28 exhibits divergent function in different cancer types." (PMID 36935008, 2023).
cancer (continued). "Results showed that TRIM28 expression was positively correlated with TMB in multiple cancer types, indicating that TRIM28 might be a robust biomarker for initiating immunotherapy in multiple cancers." (PMID 37357254, 2023). "Furthermore, TRIM28 expression was correlated with the classification of cancers such as ACC, KICH, KIRC, KIRP, LIHC, and LUSC." (PMID 37781084, 2023). "Similar to physiological SCs, TRIM28 affects stem cell features in the cancer setting." (PMID 37492743, 2023). "Also, together with MAGEA3/6, TRIM28 forms a cancer-specific ubiquitinase that targets AMPK—the “metabolic switch” in cancer, for proteasomal degradation." (PMID 36674511, 2023). "Our findings of the effect of TRIM28 on L1 retrotransposition and cDNA synthesis in different cancer models may have important biological implications for understanding evolutionary arms race between the host and L1." (PMID 37070200, 2023). "The relationship between TRIM28 and cancer development has been gradually reported." (PMID 36756159, 2023). "Moreover, the TRIM28 gene is highly expressed in different cancer types, including breast, glioma, liver, lung, gastric, kidney, ovarian, and pancreatic cancer, and higher expression frequently correlates with poor survival." (PMID 36674511, 2023). "TRIM28 is upregulated in many types of cancer where endogenous L1 mRNA expression is also high, suggesting that its suppressive effect on L1 expression may be context specific." (PMID 37070200, 2023). "Patients within each cancer group were separated in to two groups, with 8 patients demonstrating ‘High’ and 8 patients exhibiting ‘Low’ TRIM28 mRNA expression according to the reported TRIM28 mRNA expression in their tumors." (PMID 37070200, 2023). "Gene mutation and amplification are the most common genetic alterations in TRIM28 in cancers." (PMID 37781084, 2023). "In conclusion, although TRIM28 is often described as an oncogene, it may have dual roles as an oncogene or a tumor suppressor, and further research is needed to clarify the exact role of TRIM28 in the occurrence and development of cancer." (PMID 36756159, 2023). "Our study aimed to determine whether TRIM28 is a possible oncogenic target gene with important implications for immunotherapy in a variety of cancers." (PMID 37781084, 2023). "Our findings align with these observations, as we demonstrate that overexpressing TRIM28 in cancer cells leads to the recruitment of functional MDSCs, which subsequently inhibit the function and proliferation of effector T cells in KP tumor-bearing mice, ultimately compromising immune surveillance." (PMID 37865804, 2023). "The role of TRIM28 in cancer stem cells also suggests a tumor-promoting function." (PMID 36756159, 2023). "In addition, pan-cancer analyses showed that TRIM28 was highly expressed in 18 types of tumors based on the TCGA database." (PMID 37357254, 2023). "However, further studies are needed to clarify the exact role of TRIM28 in cancer stemness across distinct tumor types." (PMID 36674511, 2023). "Based on these results, TRIM28 may exert important effects on human cancers by modulating immune responses." (PMID 37781084, 2023). "Thus, we showed that full depletion of TRIM28 downregulates CD133 expression and TRIM28 can be considered as a novel regulator of the CD133-associated heterogeneity of cancer cells." (PMID 36077272, 2022). "Thus, similar to CD133, the expression of TRIM28 positively correlates with the more malignant state of cancer cells and an unfavorable clinical outcome." (PMID 36077272, 2022). "Of note, among other TIF1 members, only the association between TRIM28 high expression and cancer stemness is very robust and universal regardless of the tumor type, with higher-grade tumors exhibiting elevated TRIM28 expression." (PMID 33810347, 2021).
cancer (continued). "TRIM28 is a multifunction chromatin-binding protein, which plays an important role in many cancers." (PMID 35201498, 2021). "Thus, RIPK3 activation-dependent regulation of TRIM28 in cancer cells is likely to significantly contribute to a robust cytotoxic anti-tumor immunity." (PMID 34419074, 2021). "Collectively, with many reports presenting TRIM28 contribution to cancer, these findings suggest that regulatory networks controlling self-renewal in stem cells may also be active in some types of cancer and may constitute new cancer cell therapy." (PMID 34440702, 2021). "In addition, we demonstrate that in iPSC, TRIM28 influences the expression of the genes involved in the cell cycle, self-renewal, cell death, mobility, and other gene characteristic for cancer cells." (PMID 34440702, 2021). "These regions contain important cancer-related genes including TRIM28, SEMA3C, NOTCH1, and FAT1." (PMID 34168152, 2021). "As previously reported, TRIM28 overexpression correlates with poor prognosis in many cancer types." (PMID 34440702, 2021). "In recent years, the biological role of TRIM28 in cancer cells has come into public attention." (PMID 33817325, 2021). "However, molecular studies are needed to determine the role of TRIM28 in the acquisition or maintenance of a stem cell-like cancer phenotype across distinct types of solid tumors." (PMID 33810347, 2021). "Our data suggest the potential use of RING and PHD domains of TRIM28 as targets in cancer therapy." (PMID 34440702, 2021). "TRIM28 was shown to be necessary for the acquisition of a stem cell-like phenotype by cancer cells." (PMID 33810347, 2021). "In many tumor types, stemness-high tumors are significantly associated with a worse prognosis and among other TIF1 members, only TRIM28 might serve as a marker of cancer stemness features." (PMID 33810347, 2021). "The results showed that TRIM28 functioned as a cancer-promoting gene in BC." (PMID 33817325, 2021). "Our results indicate that only TIF1β (also known as Tripartite Motif protein 28, TRIM28) high expression is consequently associated with a “stemness high” phenotype, regardless of the tumor type, resulting in a worse prognosis for cancer patients." (PMID 33810347, 2021). "It would be interesting to investigate whether TRIM28 ubiquitinates and removes other repair proteins to complete repair and whether the expression of TRIM28 affects the therapeutic response of cancers." (PMID 33778494, 2021). "Verification of whether TRIM28 possesses the potential to serve as a druggable target may pave the way to novel anticancer therapies that directly target cancer stem cell population whilst enhancing endogenous antitumor immune response." (PMID 33076560, 2020). "We then used the PrognoScan database to investigate whether TRIM28 expression correlated with the prognosis of cancer patients." (PMID 33091876, 2020). "To determine whether TRIM28 expression differed between tumor tissues and healthy tissues, we used the Oncomine database to analyze TRIM28 mRNA levels in multiple cancer types." (PMID 33091876, 2020). "Notably, TRIM28 expression significantly impacted the prognosis of seven cancer types, including breast, lung, ovarian, brain, skin, prostate and blood cancers." (PMID 33091876, 2020). "Thus, although the prognostic value of TRIM28 expression differed among different cancer types, the results from different databases all confirmed the prognostic value of TRIM28 expression in LUAD." (PMID 33091876, 2020). "We also used the UALCAN cancer database to examine TRIM28 protein levels in various cancer tissues." (PMID 33091876, 2020).
cancer (continued). "Furthermore, a χ2 test showed that there was a significant difference when comparing the prevalence of TRIM28 expression in various levels of cancer progression (χ2 = 14.926, P = 0.002)." (PMID 30484263, 2019). "By inducing the ubiquitination and degradation of the pro-survival factor BCL2A1, TRIM28 may have an anti-tumoral activity in cancer cells whose survival depends on a high expression of BCL2A1." (PMID 30974870, 2019). "TRIM28 is highly expressed in many cancers, and its inactivation has not been previously associated with oncogenesis." (PMID 30885698, 2019). "High levels of TRIM28 expression occurs in many tumour types, but loss of TRIM28 function has not previously been implicated in human cancer." (PMID 29912901, 2018). "Our findings for the first time revealed that the expression of cancer testis antigen MAGEC2 in tumor cells depends on the existence of TRIM28, which is very important for further exploring the biological functions of MAGEC2 and TRIM28 in tumorigenesis and cancer development." (PMID 30309319, 2018). "The role of Lck in T-cell immunity may affect cancer cells in a similar manner to ACT, thereby contributing to low cancer recurrence rates seen in TRIM28 low ratio patients." (PMID 29631612, 2018). "Role of TRIM28 in cancer cells has been questioned for more than 15 years." (PMID 28851455, 2017). "In contrast to normal cells, the majority of human cancers, and cancer-derived cell lines, support variable, but typically much higher endogenous full-length L1 mRNA expression despite frequent TRIM28 upregulation." (PMID 28851455, 2017). "Furthermore, TRIM28 was the most differentially expressed gene in axitinib-sensitive cancer cell lines." (PMID 27845900, 2017). "However, several reports revealed positive correlation between the level of TRIM28 expression and cancer prognosis in specific cancer types." (PMID 28851455, 2017). "Therefore, the mode of TRIM28 action is highly context-dependent, with many reports strongly implying its’ cancer promoting features." (PMID 28851455, 2017). "Furthermore, TRIM28 is an indispensable regulator of stem cell pluripotency, facilitating self-renewal of both normal and cancer stem cells and TRIM28-dependant maintenance of CSC population certainly represents pro-tumorigenic function of TRIM28." (PMID 28851455, 2017). "It is worth to consider whether DNA damage inducing agents triggering misregulation of DNA structure through altered phosphorylation of TRIM28 may consequently result in aberrant regulation of retroelements in cancer cells." (PMID 28851455, 2017). "Interestingly, the mechanism of TRIM28-Ser824-phosphorylation-dependent regulation of chromatin relaxation was utilized by cancer cells to promote their growth." (PMID 28851455, 2017). "Axitinib is known to target cancer stem-like cells, which further supports our hypothesis that TRIM28 plays a role in the maintenance of the CSC population." (PMID 27845900, 2017). "Therefore, TRIM28 prevents genome destabilization and parallelly, blocks the path of cancer development." (PMID 28851455, 2017). "Moreover, TRIM28 was previously shown to form a cancer-specific ubiquitinase (together with MAGE-A3/6 proteins and target AMPK, a master regulator of metabolic/energy homeostasis and mitochondrial biogenesis in cancer cells for proteasomal degradation." (PMID 27845900, 2017). "Thorough analyses are further needed to verify whether TRIM28 possess the potential to become a new anti-cancer target." (PMID 28851455, 2017).
cancer (continued). "Moreover, TRIM28 depletion reduced the ability of cancer cells to induce tumor growth when subcutaneously injected in limiting dilutions." (PMID 27845900, 2017). "Trying to answer the question whether TRIM28 acts as a tumor-inhibiting or tumor-stimulating factor, we delineate the cancer-related roles of TRIM28." (PMID 28851455, 2017). "This reciprocal relationship between EMT and CSCs might have many implications in tumor progression and previously demonstrated involvement of TRIM28 protein in regulation of EMT implies its role in cancer stem cell maintenance." (PMID 28851455, 2017). "Also, tight regulation of retroelement repression suggests that TRIM28 acts as an anti-tumorigenic factor, safeguarding normal cell from cancer transformation in a phosphorylation-dependent manner." (PMID 28851455, 2017). "The multitude and complexity of TRIM28 actions in cancer make it difficult to unambiguously establish whether TRIM28 is a cancer promoting agent or possess anti-proliferative activity." (PMID 28851455, 2017). "Mouse conditional knockout studies have clearly indicated that Trim28 and related family member can behave as tumor suppressors; however, other studies indicate that Trim28 has elevated levels and oncogenic effects in a variety of cancers." (PMID 24983967, 2014). "Moreover, TRIM28’s capacity to engage with the immune system, especially via its function in immune regulation and inflammation, emphasizes the possibility of using it as a therapeutic target in the tumor microenvironment in addition to cancer." (PMID 39534556, 2024). "Consequently, it is important to note that TRIM28 affects many types of cancer." (PMID 39534556, 2024). "Interestingly, Trim28-targeted transcription regulators of the cell cycle, cell death, and cancer, supporting the idea that self-renewal-specific pathways may also be active in certain cancers." (PMID 37492743, 2023). "Targeting TRIM28 may effectively prevent cancer metastasis by eliminating CSCs." (PMID 36756159, 2023). "Additionally, Trim28-based gene repression machinery has a grounded place in the stem cell regulatory mechanisms, and recent reports demonstrate the involvement in cancer development and progression, especially by supporting the cancer stem cell population." (PMID 36361869, 2022). "Our results demonstrate that high expression of only one member of the TIF1 family, namely TIF1β (also known as Tripartite Motif protein 28, TRIM28) is consequently associated with enriched cancer stemness across the tested solid tumor types, resulting in a worse prognosis for cancer patients." (PMID 33810347, 2021). "Therefore, regulatory networks dependent on TRIM28 signaling that control self-renewal in stem cells may also be active in some types of cancer cells." (PMID 34440702, 2021). "Among other TIF1 members, only TRIM28 might serve as a marker of cancer stemness features." (PMID 33810347, 2021). "In addition, TRIM28 has an important role in the oncogenesis in different cancer types." (PMID 34500575, 2021). "RIPK3 activation inhibits the chromatin binding activity of TRIM28 leading to the transcriptional activation of cytokines, which then promotes immunoregulatory processes, such as dendritic cell maturation and further cytokine production, which then contribute to anti-cancer responses." (PMID 34419074, 2021). "Thus, TRIM28 activity contributes to the development of several cancers." (PMID 34298819, 2021). "There were no TRIM28 mutations in individuals with other childhood or adult cancers." (PMID 30885698, 2019). "We found no other cancers in individuals carrying TRIM28 mutations." (PMID 30885698, 2019). "In addition, as an important positive regulator of MAGEC2, TRIM28 might be a potential target for cancer therapy." (PMID 30309319, 2018). "Moreover, we will discuss whether the complexity of TRIM28 engagement in cancer biology makes TRIM28 a possible candidate for targeted anti-cancer therapy." (PMID 28851455, 2017).